HNF1B (HNF1 homeobox B)
Diseases named in the same sentence as HNF1B in open-access papers (continued):
Sharing a sentence is not in itself a finding about the gene and the disease.
diabetes (continued). "HNF1A, GCK, and HNF1B are the genes presenting the most variants in both level 1 and level 2 databases, indicating that most of the monogenic diabetes-associated variants have been reported in these genes, as well as most of the ones confirmed as pathogenic or likely pathogenic." (PMID 38635808, 2024). "Nevertheless, due to the initial description of HNF1B-deficiency as a syndrome characterized by kidney disease and diabetes, the liver involvement in HNF1B deficiency has been frequently overlooked, and only a few studies reported a comprehensive evaluation of the hepatic disease phenotypes." (PMID 36672242, 2023). "We identified a genomic risk locus at HNF1B for diabetes (NC_000017.11:g.37741165C>G, rs7501939, p=6×10−17), increased ALT (NC_000017.11:g.37713312C>T, rs17138478, p=6×10−25), AST (NC_000017.11:g.37713312C>T, rs17138478, p=4×10−12) and GGT (NC_000017.11:g.37717101A>G, rs718961, p=2×10−52)." (PMID 36109160, 2023). "The evidence that carriers of the HNF1B deficiency are at a greater risk for diabetes mellitus raised the question of whether transplant management must be modified to avoid drugs that can cause hyperglycemia." (PMID 36672242, 2023). "Indeed, patients with HNF1B-deficient syndrome rarely show only diabetes and this diagnosis should be suspected at diabetes onset in all the patients with renal cysts and/or other suggestive extra-pancreatic features, even when a family history is absent." (PMID 36672242, 2023). "Together these findings are consistent with a model in which HNF1B haploinsufficiency in vivo in patients might lead to reduced β cell numbers at birth and increased diabetes susceptibility later in life." (PMID 35487213, 2022). "RNA-seq shed light on the genes that are differentially regulated in response to homozygous or heterozygous knockdown and might underlie HNF1B-associated diabetes onset in humans." (PMID 35487213, 2022). "Similarly, mutations affecting HNF1β in humans cause phenotypes mainly associated with kidney disorders, diabetes mellitus, and MODY." (PMID 35235779, 2022). "The modulation of these factors during fetal life by environmental stimuli could compensate in part for the decrease in HNF1B expression, explaining the variable penetrance of HNF1B-associated diabetes." (PMID 34450036, 2021). "Deleterious heterozygous variants in HNF1B, such as the frequently reported whole gene deletion (about 50% of cases), lead to heterogeneous malformations of the kidney and/or the urinary tract and/or diabetes mellitus." (PMID 33625646, 2021). "The second HNF1B variant, c.494G > A, was identified in 6 years and nine-month-old Pakistani boy who was found to have a high creatinine level (108.0 μmol/L) at the initial diagnosis of diabetes at the age of around 4- years." (PMID 34373539, 2021). "HNF1B-associated disease is characterized by abnormalities in kidney structure and function, diabetes mellitus (MODY5 type), hyperuricemia, elevated liver cholestatic enzymes, pancreatic and genital tract malformations (synonym – renal cysts and diabetes syndrome, RCAD)." (PMID 35474932, 2021). "For example, HNF1B mutations are associated with diabetes mellitus, and NPHP1 genetic variants may cause multisystemic diseases and Joubert syndrome, among others." (PMID 34295353, 2021). "As an example, MODY5 diabetes (HNF1B-associated) can be induced by a diversity of mutations including several splice-site, non-sense, missense, and frame-shift mutations or whole gene deletions, all of which result in a diabetes." (PMID 34295307, 2021). "Diabetes mellitus is the most frequent extrarenal phenotype associated with HNF1B mutations." (PMID 32708349, 2020). "However, diabetes in patients with HNF1B mutations rarely develops in childhood but rather manifests in the third or fourth decades of life." (PMID 32708349, 2020). "HNF1B-associated diabetes mellitus represents ∼1% to 6% of MODY cases in the United Kingdom." (PMID 32756155, 2020).
diabetes (continued). "A French group studied the diabetes phenotype of patients with HNF1B mutations in more detail." (PMID 31066763, 2019). "Missense mutations in HNF1β are commonly associated with both monogenic diabetes and kidney disease, and a number of in-vitro functional studies have demonstrated that missense mutations in HNF1β lead to impaired DNA-binding and reduced transactivation potential." (PMID 29764441, 2018). "We would hypothesize that pancreatic insufficiency and diabetes in HNF1B-associated disease are associated, as they are secondary to reduced exocrine and endocrine cells as a result of pancreatic hypoplasia." (PMID 30094008, 2018). "HNF1β mutations are commonly designated as renal cyst and diabetes syndrome." (PMID 29479522, 2017). "In addition, heterozygous protein truncating mutations were detected in the GCK, HNF1A, and HNF1B genes in seven individuals with diabetes." (PMID 29207974, 2017). "Although both studies included a similar number of participants and all had HNF1B-associated disease identified secondary to renal disease or diabetes, the median age at inclusion was only 5.5 years (range 0.8–17) compared with 17 years (range 4–65) in our UK cohort." (PMID 27234567, 2016). "The penetrance of diabetes in patients with HNF1B mutations is unknown and may present in late adult life." (PMID 24705260, 2013). "Association between HNF1B variants and endometrial cancer by diabetes status." (PMID 22299039, 2012). "To determine whether the associations of HNF1B variants and endometrial cancer were influenced by diabetes, we examined the OR for the SNP-endometrial cancer relationship among diabetics and non-diabetics separately." (PMID 22299039, 2012). "However, the marked insulin deficiency often seen in HNF1B-diabetes could markedly increase the risk of diabetic ketoacidosis." (PMID 39025920, 2024). "Variants and deletions of the HNF1B gene are characteristic in renal cysts and diabetes, which may be explained by the expression of the HNF1B gene in the kidney and pancreas; HNF1B is also expressed in the Wolffian and Müllerian ducts and plays a central role in their formation." (PMID 35883945, 2022). "Notably, this model might more closely recapitulate the mechanisms underlying HNF1B-associated diabetes in MODY5 patients with nonsense or frameshift mutations, in which the HNF1B protein function is more severely compromised." (PMID 34450036, 2021). "Likewise, the reduced SOX11 expression in D13.1βHet SOX2+ progenitors and early MPCs found in our HNF1B-deficient pancreatic cell differentiation model could at least partially explain the organ hypoplasia found in patients with HNF1B-associated diabetes." (PMID 34450036, 2021). "In this work we uncover an exhaustive list of potential HNF1B gene targets during human pancreas organogenesis whose downregulation might underlie HNF1B-associated diabetes onset in humans, thus providing an important resource to understand the pathogenesis of this disease." (PMID 34450036, 2021). "We evaluated 28 unrelated patients with clinical suspicion of HNF1B mutation because of the concomitant presence of diabetes mellitus (DM) or prediabetes and renal cysts." (PMID 31066763, 2019). "Therefore, the exact prevalence and spectrum of neurodevelopmental disorders in HNF1B-associated renal disease and diabetes remains unknown." (PMID 27234567, 2016). "Whether diabetes status influences the association between HNF1B and endometrial cancer therefore remains unclear; examination of potential interaction between diabetes status and HNF1B in other endometrial cancer studies is warranted." (PMID 22299039, 2012). "Syndromic Diabetes: Arises from mutations in pleiotropic transcription factors (GLIS3, GATA6, HNF1B) or metabolic transporters (SLC19A2, WFS1)." (PMID 41614934, 2026).
diabetes (continued). "Our findings broaden the molecular and clinical spectrum of HNF1B-related diabetes, and emphasize the importance of considering HNF1B defects in children with transient neonatal hyperglycemia." (PMID 41986760, 2026). "Examples include the 17q12 [HNF1B] deletion (Renal Cysts and Diabetes) and the 1q21.1 [RBM8A] proximal deletion." (PMID 41094176, 2026). "Because these factors—including GLIS3, PAX6, GATA6, HNF1B, and NEUROG3—are pleiotropic regulators active in multiple organ systems, their deficiency rarely causes isolated diabetes." (PMID 41614934, 2026). "Variants in the genes GCK, HNF1A, HNF1B, HNF4A, ABCC8, INS, and INSR were the main contributors to the genetic pathogenesis of hereditary diabetes mellitus in the Russian cohort." (PMID 39859454, 2025). "In the pancreas, HNF-1β regulates genes essential for beta-cell function and insulin production, directly linking its haploinsufficiency to the onset of diabetes." (PMID 41009948, 2025). "Reports from India have described an even broader mutation spectrum, including ABCC8, HNF1B, and INS variants, collectively accounting for a substantial proportion of monogenic diabetes diagnoses." (PMID 41367630, 2025). "HNF1B variants have variable penetrance, with the classical phenotype, including CKD, gout, and diabetes." (PMID 40630292, 2025). "HNF1B mutations are associated with CAKUT, a slowly progressive decline in kidney function, pancreatic abnormalities, diabetes, and neurological deficits, among other phenotypes." (PMID 40313719, 2025). "Recommendation: There is insufficient data to recommend or refute the preferential use of insulin or any other medication in HNF1B-diabetes or mitochondrial diabetes." (PMID 39025920, 2024). "Of the 168 individuals with HNF1B-diabetes, for whom treatment data after the genetic diagnosis was available, 132 (79%) used insulin, but it is not known if other medications had been tested." (PMID 39025920, 2024). "In the included case reports and case series, which were mainly cross-sectional, most patients diagnosed with HNF1B-diabetes or MD seem to have commenced insulin treatment at some stage." (PMID 39025920, 2024). "We systematically analyzed evidence for precision treatments for GCK-related hyperglycemia, HNF1A-, HNF4A- and HNF1B-diabetes, and mitochondrial diabetes (MD) due to m.3243 A > G variant, 6q24-transient neonatal diabetes mellitus (TND) and SLC19A2-diabetes." (PMID 39025920, 2024). "Thus, by analogy, it can be concluded that rare severe variants in the CACNA1E gene may cause monogenic diabetes, as is the case with the HNF1β, GCK or KCNJ11 genes, while common single nucleotide alterations are associated with an increased risk of type 2 diabetes." (PMID 38932873, 2024). "Of the three patients with a known diabetes, two were diagnosed with new-onset diabetes after transplantation (NODAT), one with MODY 5 (HNF1B mutation)." (PMID 38103064, 2024). "HNF1B prevalence is probably underestimated in this study, because we focused on patients with suspected ADTKD, whereas HNF1B diagnosis can also be made with genetic testing for diabetes or congenital anomalies of the kidney and urogenital tract." (PMID 38707821, 2024). "What is the optimal glucose-lowering therapy in the two commonest subtypes of syndromic diabetes: HNF1B-diabetes and Mitochondrial Diabetes (MD) due to m.3243 A > G in the MT-TL1 gene?" (PMID 39025920, 2024). "A yield of 2.4% and 2.9% for HNF1B etiology for diabetes was found in a UK and Chinese study respectively." (PMID 37794142, 2023). "Those diverse cases point to the fact that HNF1B-related MODY is a rare form of diabetes, and its diagnosis requires a high degree of suspicion based on clinical presentation and family history." (PMID 37511676, 2023). "Two PTVs and one pathogenic missense variant in HNF1B were identified in four UKB participants of European ancestry, one of whom had diabetes (p=0.06)." (PMID 36109160, 2023).
diabetes (continued). "In this observational study, the authors describe 10 patients with several HNF1B molecular defects inducing different clinical presentations with a significant delay (16.5 years) between the diagnosis of diabetes and that of HNF1B-MODY." (PMID 36793123, 2023). "HNF1B/MODY represents up to 6% of all MODY cases and is one of the most frequent causes of syndromic diabetes, showing a decrease in insulin secretion with progressive worsening of blood glucose control." (PMID 36672242, 2023). "Mutations in and deletions of HNF1β cause autosomal dominant tubule interstitial kidney disease (ADTKD) subtype HNF1β, which is characterized by renal cysts, diabetes, genital tract malformations, and neurodevelopmental disorders." (PMID 35554666, 2022). "In our whole study, 16/297 (5.4%) of patients had monogenic diabetes due to either a partial or whole gene deletion (14 HNF1B, 1 HNF1A and 1 HNF4A)." (PMID 34789499, 2022). "MODY is monogenic diabetes caused by a single gene mutation of either HNF-1α, HNF-1β, HNF-4α, HNF-1β, glucokinase, PAK4, KLF11, neurogenic differentiation 1 (neuroD1), and insulin (INS)." (PMID 35956399, 2022). "Genes implicated in monogenic diabetes include several encoding transcription factors involved in pancreatic beta cell development (e.g. HNF1A, HNF1B, HNF4A, PDX1, GATA4, GATA6)." (PMID 35618782, 2022). "We also re-contacted the clinicians of patients with m.3243A>G and HNF1B diabetes identified by tNGS and obtained follow-up information on 15 cases (5/18 cases with HNF1B and 10/24 cases with m.3243A>G)." (PMID 34789499, 2022). "The study showed that in a cohort of 201 adult patients with HNF1β defects, diabetes was present in 159 patients." (PMID 35480487, 2022). "In men, the effects of carbohydrate intake >65 E% on the development of diabetes differed according to the rs4430796 genotype in HNF1B." (PMID 35277013, 2022). "78% of patients in our study with HNF1B diabetes had a large partial (one or more exons) or whole gene deletion." (PMID 34789499, 2022). "Maturity-onset of diabetes of the young is associated with defects in 14 different genes, the most common ones being GCK, HNF4A, HNF1A, and HNF1B." (PMID 35640144, 2022). "Syndromic monogenic diabetes genes (particularly m.3243A>G and HNF1B) should be routinely tested in patients with suspected MODY that do not have typical features of a genetic syndrome." (PMID 34789499, 2022). "More than 20 causal genes have been linked to monogenic diabetes so far, the strongest evidence and highest prevalence having the transcription factors HNF1A, HNF4A, HNF1B and the GCK gene encoding the glucokinase enzyme." (PMID 34440499, 2021). "Thus, the level of HNF1B, combined with environmental stimuli, could define the number of pancreatic progenitor cells generated during development and therefore contribute to the susceptibility to diabetes during childhood/adulthood." (PMID 34295307, 2021). "The HNF family of TFs is implicated in mature onset diabetes of the young (MODY), and mutations in the HNF4α, HNF1α, and HNF1β genes cause MODY, a form of non-insulin-dependent diabetes mellitus." (PMID 34771521, 2021). "After assessing maternal diseases and symptoms: chronic kidney disease (CKD), kidney cysts, gynecological problems, diabetes mellitus and in the presence of a newborn with suspected HNF1B nephropathy a genetic test was also performed for the mother." (PMID 35474932, 2021). "Heterozygous mutations in the human HNF1B are associated with MODY, which is characterised by early onset diabetes, pancreas hypoplasia and multicystic kidney dysplasia, but also with kidney diseases and multi-organ disorders." (PMID 34299172, 2021). "The broad expression of HNF1B in UB, liver, and pancreas explains additional extrarenal features, such as “Maturity Onset Diabetes of the Young Type 5” (MODY5) and defects of the urinary collecting system." (PMID 33625646, 2021).
diabetes (continued). "We present the clinical case of a 15 year-old patient with a family history of diabetes mellitus and a classical MODY type 5 (MODY5) phenotype involving the pancreas and kidney, with a novel, unreported mutation in the hnf1b gene." (PMID 32864159, 2020). "Some syndromic CAKUT encompass characteristic extrarenal manifestations, such as hearing loss and neck anomalies in BOR syndrome (EYA1), optic nerve coloboma in renal coloboma syndrome (PAX2), and hyperuricemia and diabetes in RCAD syndrome (HNF1B)." (PMID 32164334, 2020). "These open chromatin regions were significantly enriched in binding sites of CUX2 and HNF6 as well as several other TFs with previously established functions in pancreatic development and links to monogenic diabetes, including HNF1B, FOXA2, and PDX1." (PMID 31883919, 2020). "HNF1β-MODY (MODY5) is an uncommon form of monogenic diabetes that is often complicated by a wide array of congenital morphological anomalies of the urinary tract, including renal cysts." (PMID 29764441, 2018). "We have taken the alternative approach of investigating the DNA methylation profile of these two HNF1B genotype groups along with controls matched for age, gender and diabetes status using the Illumina 450K DNA methylation array (total sample n = 60)." (PMID 30021660, 2018). "The pyrosequencing data was converted into beta values (by dividing the pyrosequencing % values by 100) and regressed against HNF1B status with covariates for age, diabetes status, gender and cell composition as in the initial analysis." (PMID 30021660, 2018). "Primarily, heterozygous mutations in HNF1β cause a complex Renal cysts and Diabetes syndrome (RCAD) characterised by early onset diabetes (MODY5), liver dysfunction and pancreatic hypoplasia." (PMID 29764441, 2018). "Among individuals with young onset and adult onset diabetes, 40 individuals (1.8% of subjects with early onset diabetes and 0.6% with late onset) were carriers of known pathogenic missense mutations in the GCK, HNF1A, HNF4A, HNF1B, ABCC8, and INS genes." (PMID 29207974, 2017). "For the human-centric brain network comparisons, u(HB, MB), the genes IKZF1 and HNF1B, which are related to acute lymphoblastic leukemia and diabetes mellitus type 2 respectively, were found among the centralmost genes." (PMID 29161290, 2017). "Seven such mutations were observed in MODY genes in which heterozygous loss-of-function variants are known to be pathogenic for diabetes – three each in the GCK and HNF1A genes and one in the HNF1B gene." (PMID 29207974, 2017). "Having established which of the circulating miRNAs seem to be dependent on HNF1A or HNF1B defects, we set about replicating the findings in our UK group of patients with monogenic diabetes." (PMID 27059371, 2016). "Of these, 36 probands were seen in the adult diabetes clinic, and were tested for one or more of the monogenic diabetes genes GCK, HNF1A, HNF4A and HNF1B or the mitochondrial m.3243A>G mutation." (PMID 27330718, 2016). "The objective of our study was to identify miRNAs under the transcriptional control of HNF1β or HNF1α and assess the potential of such miRNAs as biomarkers of monogenic diabetes." (PMID 27059371, 2016). "The median age at diagnosis of diabetes was also lower in those with HNF1B-related disease at 16.5 years (IQR 12-26.8) compared to those without (median age 32.5, IQR 15.3-49.8), p < 0.0001." (PMID 26022541, 2015). "Furthermore, several genome-wide association studies suggest that diabetes mellitus and prostate cancer share certain genetic factors, including the HNF1β and JAZF1 genes, and a previous study suggested that JAZF1 might represent a potential target against diabetes and obesity." (PMID 23406686, 2013). "In the UK replication study, we did not observe a difference in cystatin C levels between the UK HNF1A-MODY and other diabetes types, except HNF1B-MODY." (PMID 22350134, 2013).